RNF115 (ring finger protein 115)
Diseases named in the same sentence as RNF115 in open-access papers (continued):
Sharing a sentence is not in itself a finding about the gene and the disease.
autoimmune disease (2 papers, 2022 to 2023). A disorder resulting from loss of function or tissue destruction of an organ or multiple organs, arising from humoral or cellular immune responses of the individual to their own tissue constituents. "NOSTRIN connects to another nitric oxide gene, NOS3, RNF115 to the RAS oncogene family member RAB7A, while SPRR2A connects with EVPL (associated with squamous cell cancer and autoimmune disease)." (PMID 38030619, 2023). "Our findings highlight RNF115‐mediated regulation of distinct cellular processes may play different roles in antimicrobial and autoimmune disease and defining the mechanisms underlying this regulation would help explain the etiology of certain infectious and autoimmune diseases." (PMID 35343654, 2022).
hepatocellular carcinoma (2 papers, 2025). A malignant tumor that arises from hepatocytes. "Subsequently, RNF115 interacts with dihydroorotate dehydrogenase (DHODH) to promote its K27 ubiquitination and inhibit the autophagic degradation of DHODH to resist ferroptosis and promote hepatocellular carcinoma (HCC) progression." (PMID 40088428, 2025).
atherosclerosis (1 paper, 2022). A disease characterized by the build-up of fatty material and calcium deposition in the arterial wall resulting in partial or complete occlusion of the arterial lumen. "Upon treatment with CRA, upregulation of RNF115 genes, followed by expression of E3 ubiquitin-protein ligase RNF115 (FC = 16.09) with protein accession number Q9Y4L5, was found to be linked to atherosclerosis pathways." (PMID 36002804, 2022).
cardiac hypertrophy (1 paper, 2026). "RNF115 knockdown attenuates Ang II-induced cardiomyocyte hypertrophy in vitro, whereas cardiomyocyte-specific RNF115 knockout protects against TAC-induced cardiac hypertrophy and dysfunction in vivo." (PMID 42294585, 2026).
chromophobe renal cell carcinoma (1 paper, 2024). Chromophobe renal cell carcinoma is a rare subtype of renal cell carcinoma, originating from the intercalating cells of the collecting ducts and macroscopically manifesting as a well-circumscribed, highly lobulated, solid tumor that is usually diagnosed at an early stage. "RNF115 has emerged as a significant gene in our study, as well as in the broader study of renal tumours, particularly in differentiating between chromophobe renal cell carcinoma (ChRCC) and renal oncocytoma (RO)." (PMID 39684226, 2024).
gastric adenocarcinoma (1 paper, 2020). "Data from tissue microarray and immunohistochemistry demonstrate that RNF115 protein displayed moderate or high expression levels in most gastric adenocarcinoma cells." (PMID 32980859, 2020). "In the present study, it was found that the expression of RNF115 is increased in gastric adenocarcinoma samples compared to normal gastric tissue." (PMID 32980859, 2020).
heart failure (1 paper, 2026). Inability of the heart to pump blood at an adequate rate to meet tissue metabolic requirements. "RNF115 expression is significantly elevated in heart tissues from patients with heart failure, in mice subjected to transverse aortic constriction (TAC) surgery, and in cardiomyocytes treated with angiotensin II (Ang II)." (PMID 42294585, 2026).
oncocytic neoplasm (1 paper, 2024). A usually benign neoplasm composed of large cells with abundant eosinophilic granular cytoplasm. "Research indicates that RNF115 is consistently expressed in all cases of renal oncocytoma and in oncocytic neoplasms favouring oncocytoma, but it is barely detectable in ChRCC." (PMID 39684226, 2024).
sarcopenia (1 paper, 2026). Progressive decline in muscle mass due to aging which results in decreased functional capacity of muscles. "By using ML algorithms and expression analysis techniques, this study further validated several URGs including CBLB, PSMD6, RNF115, SMAD3, UCHL3 and ZBTB16 as potential markers associated with sarcopenia." (PMID 41560007, 2026).
thyroid carcinoma (1 paper, 2024). "In our investigation, we endeavor to unravel the putative function and inherent mechanism through which RNF115 influences the evolution of thyroid carcinoma (THCA)." (PMID 38376606, 2024).
trigonocephaly (1 paper, 2017). "Likewise, none of the genes duplicated in patient 6 (NBPF20, GPR89A, PDZK1, CD160, RNF115) are known to cause trigonocephaly." (PMID 28724436, 2017).
uterine corpus endometrial carcinoma (1 paper, 2025). A endometrial carcinoma (disease) that involves the body of uterus. "Gene expression analysis showed limited overall significance, but TAF1 was notably upregulated in uterine corpus endometrial carcinoma (UCEC), while RNF115 and RNF141 were downregulated in the same cancer type." (PMID 40591126, 2025).
cancer (16 papers, 2008 to 2025). A tumor composed of atypical neoplastic, often pleomorphic cells that invade other tissues. "The E3 ubiquitin ligase RING finger protein 115 (RNF115), also known as breast cancer-associated gene 2 (BCA2), has been linked with the growth of some cancers and immune regulation, which is negatively correlated with prognosis." (PMID 38129372, 2023). "From a mechanistic perspective, RNF115 activated the Raf-1 pathway and enhanced cancer cell cycle progression by degrading CDK10 in THCA cells." (PMID 38376606, 2024). "However, the function of RNF115 in other cancers is unknown." (PMID 32980859, 2020).
tumor (11 papers, 2012 to 2025). "In addition, analysis of clinical samples revealed that YBX1 and RNF115 were upregulated in HCC tumours and associated with poor prognosis." (PMID 40088428, 2025). "In contrast, knockdown of RNF115 inhibited tumour proliferation, and this effect was rescued by Fer‐1, suggesting that RNF115 inhibits ferroptosis in vivo." (PMID 40088428, 2025). "RNF115, an E3 ubiquitin ligase, regulates the ubiquitin modification of various substrates and is essential for the progression of tumours." (PMID 40088428, 2025). "In vivo, overexpression of RNF115 significantly promoted the proliferative capacity of xenograft tumours." (PMID 40088428, 2025). "The significant enhancement of cell proliferation and tumor growth in THCA is observed upon the upregulation of RNF115." (PMID 38376606, 2024). "The data showed that RNF115 overexpression augmented THCA tumor volume, while RNF115 knockdown impeded tumor growth (p < 0.05)." (PMID 38376606, 2024). "Both paired and unpaired samples showcased elevated RNF115 expression in THCA tumor tissues (p < 0.01)." (PMID 38376606, 2024). "Further evaluation of RNF115 expression in human THCA tumors and adjacent normal tissues (n = 113) revealed significantly elevated RNF115 levels in tumor tissues (p < 0.01)." (PMID 38376606, 2024). "Our initial investigation centered on determining the expression levels of RNF115 in THCA tumor tissues and cell lines, aiming to shed light on its role in THCA progression." (PMID 38376606, 2024). "Analysis of correlations indicated that THCA patients with high RNF115 expression had larger tumor size (≥ 3 cm3) and advanced clinical stage (stage N1 and TNM stage III-IV)." (PMID 38376606, 2024). "Meanwhile, RNF115 overexpression promotes the levels of Ki67 (a cell proliferation marker) and N-cadherin, as well as inhibiting E-cadherin expression in tumor tissues." (PMID 38376606, 2024). "The suppressive influence of RNF115 on CDK10 expression was further corroborated in THCA tumor tissues through IHC." (PMID 38376606, 2024). "For exploring the function of RNF115 in tumor cell metabolism, the correlation between high/low expression of RNF115 and glycolytic process or β-catenin pathway was analyzed by GSEA." (PMID 33509267, 2021). "On the other hand, relying on IHC analysis, we have detected 29 cases of low RNF115 expression and 51 cases of high expression in total from the tumor specimens collected from 80 LUAD patients (cohort 2)." (PMID 33509267, 2021). "In the current study, we aimed to explore the correlation between RNF115 and LUAD prognosis, the functions of RNF115 on tumor cell proliferation and metabolic remodeling in LUDA, and their potential underlying mechanisms." (PMID 33509267, 2021). "In details, the average expression level of RNF115 in the 59 normal tissues was significantly (P < 0.001) lower than that in the 526 tumorous tissues in LUAD patients." (PMID 33509267, 2021). "The relationship between autophagy and tumor growth and metastasis regulated by RNF115 requires further elucidation." (PMID 32980859, 2020). "We further established an animal model of peritoneal metastasis by injection of pLVX-shcontrol/BGC823 cells or pLVX-shRNF115/BGC823 cells into mice to explore the effects of RNF115 on tumor metastasis." (PMID 32980859, 2020). "The tumor weight in the pLVX-shRNF115 group was significantly lower than that in the control group, suggesting that knockdown of RNF115 inhibits the growth of BGC823 cells in vivo." (PMID 32980859, 2020). "However, the depletion of RNF115 reduced the basal activation levels of NF-κB in non-tumor MCF-12F cells." (PMID 38129372, 2023). "Through analyzing the patient data collected from both TCGA database and Shanghai Chest Hospital, Shanghai Jiao Tong University, we observed the substantially high expression of RNF115 in tumorous tissues from LUAD patients at both protein and transcriptional levels." (PMID 33509267, 2021).
tumor (continued). "In addition, through TUNEL, we observed that the rate of tumor cell apoptosis in mice was significantly (P < 0.01) elevated by RNF115 knockdown (shRNF115 1#) but significantly (P < 0.01) suppressed by RNF115 overexpression (oeRNF115)." (PMID 33509267, 2021). "Similarly, compared to the control at day 33, RNF115 knockdown (shRNF115 1#) significantly (P < 0.001) decreased the tumor weight in mice, while RNF115 overexpression (oeRNF115) significantly (P < 0.001) increased the tumor weight in mice." (PMID 33509267, 2021). "RNF115 triggers cell proliferation, EMT, and tumor metastasis by ubiquitinating and degrading CDK10." (PMID 38376606, 2024). "Enhanced expression of RNF115 fostered cell proliferation, tumor growth, and the exacerbation of epithelial-mesenchymal transition (EMT) in THCA, while also promoting tumor lung metastasis." (PMID 38376606, 2024). "RNF115 induces a significant arrest of the G1 phase of LAC cells to achieve the function of inhibiting cell viability in vitro, further reducing tumor proliferation in xenograft models." (PMID 35132330, 2022). "Depletion of several ubiquitinases and proteasome components (DTX3L, UBE2E1, RNF31, RNF115, USP2, USP42, PSMC3, and PSMD10) were also found to inhibit tumor cell migration." (PMID 31278301, 2019). "RNA‐seq and RNA‐Bis‐seq analysis showed that RNF115 mRNA and its m5C modification level were elevated in HCC tumours, with the m5C modification site located in the 3′‐UTR, as confirmed by methylated RNA immunoprecipitation (MeRIP)‐quantitative polymerase chain reaction (qPCR)." (PMID 40088428, 2025). "Functionally, RNF115 was shown to induce THCA cell proliferation and tumor growth." (PMID 38376606, 2024).
infection (6 papers, 2014 to 2023). The state of being infected such as from the introduction of a foreign agent such as serum, vaccine, antigenic substance or organism. "Consistently, endogenous ubiquitination analysis revealed that total or K63-linked ubiquitination of MITA was significantly decreased in RNF115-knockdown THP-1 cells or in RNF115-deficient MLFs after infection with HSV-1." (PMID 33139700, 2020). "Moreover, loss of RNF115 also increased cytokine responses and affected infection‐induced tissue damage in vivo." (PMID 36281581, 2022). "We then used infection assays to assess whether Salmonella survival is affected by loss of RNF115." (PMID 36281581, 2022). "We reconstituted the empty vector, RNF115 and its enzymatic inactive mutant RNF115 (C228A/C231A) [designated as RNF115(2CA)] in Rnf115−/− MLFs followed by infection with VSV or HSV-1 or transfection with poly(I:C) or dsDNA." (PMID 33139700, 2020). "The results from qRT-PCR analysis suggested that the expression of Ifnb, Isg56, and Ip10 was significantly increased in Rnf115−/− BMDCs and MLFs compared to the wild-type counterparts after infection with VSV, SeV, or EMCV, or transfection with poly(I:C)." (PMID 33139700, 2020). "Results from qRT-PCR analysis showed that the expression of Ifnb, Il6, and Ccl5 in the hearts and brains of Rnf115−/− mice was higher than that of wild-type littermates at day 4 after EMCV infection." (PMID 33139700, 2020). "Besides estrogen, treatment with proinflammatory cytokines such as interleukin 6 (IL-6) and tumor necrosis factor alpha (TNFα) and infection with RNA viruses also induce the upregulation of RNF115 in various cell lines and primary human and mouse cells." (PMID 35844553, 2022). "However, RNF115 KO mice showed significantly reduced infection/inflammation‐dependent tissue damage and recruitment of CD3 T‐cells." (PMID 36281581, 2022). "Consistently, the expression of Ifnb, Il6, or Isg56 and the production of IFN-β, IL-6, and TNF were significantly impaired in primary Rnf115−/− MLFs or BMDCs compared to the wild-type counterparts after infection with HSV-1, or transfection with dsDNA ligands or cGAMP." (PMID 33139700, 2020). "Results from endogenous immunoprecipitation assays suggested that RNF115 was constitutively associated with MAVS without infection, and VSV infection or transfection of poly(I:C) impaired their associations in MLFs or bone marrow-derived dendritic cells (BMDCs)." (PMID 33139700, 2020).
bacterial infection (2 papers, 2022 to 2023). "Loss of RNF115 protein or ligase activity enhanced phagosomal maturation and increased cytokine responses to bacterial infection, suggesting that both innate immune signalling from the phagosome and phagolysosomal trafficking are controlled through ubiquitylation." (PMID 36281581, 2022). "A recent study has demonstrated that RNF115 negatively regulates phagosome maturation and host response to bacterial infection." (PMID 38129372, 2023). "In conclusion, RNF115 and phagosomal ubiquitylation are important regulators of innate immune functions during bacterial infections." (PMID 36281581, 2022). "Recent studies suggest that Rnf115 knockout promotes the translocation of TLRs from the endoplasmic reticulum to the Golgi apparatus and then to the lysosomes and cell membrane, leading to greater resistance to bacterial infection in Rnf115 knockout mice." (PMID 38129372, 2023).
RNF115 also shares sentences with these, for which no sentence is quoted: lymph node metastasis (3 papers); AIDS (2); infectious disease (1); metastatic disease (1); Moyamoya disease (1); oncocytoma (1); psoriasis (1); renal oncocytoma (1); renal tumours (1); Sepsis (1); squamous cell carcinoma (1).